HRC (histidine rich calcium binding protein)
Description:
May play a role in the regulation of calcium sequestration or release in the SR of skeletal and cardiac muscle.
Synonyms: MGC133236
Tractability: Antibody: UniProt predicts a signal peptide or a membrane-spanning region.
Gene: Protein-coding gene on chromosome 19 (49,151,194 to 49,155,432, reverse strand). Ensembl gene ENSG00000130528.
Subcellular location: Sarcoplasmic reticulum lumen
Subcellular location (Human Protein Atlas): Endoplasmic reticulum; Cytosol; Mitochondria
Pathways (Reactome):
Metabolism of proteins: Post-translational protein phosphorylation; Regulation of Insulin-like Growth Factor (IGF) transport and uptake by Insulin-like Growth Factor Binding Proteins (IGFBPs)
Gene Ontology:
Molecular function: ATPase binding; calcium ion binding; protein binding; transmembrane transporter binding; calcium ion sequestering activity
Biological process: positive regulation of heart contraction; positive regulation of heart rate; positive regulation of relaxation of cardiac muscle; regulation of calcium ion transmembrane transport; regulation of cell communication by electrical coupling involved in cardiac conduction; regulation of cytosolic calcium ion concentration; regulation of heart rate; regulation of release of sequestered calcium ion into cytosol by sarcoplasmic reticulum; muscle contraction; regulation of cardiac muscle contraction by regulation of the release of sequestered calcium ion
Cellular component: endoplasmic reticulum; Z disc; endoplasmic reticulum lumen; sarcoplasmic reticulum lumen; sarcoplasmic reticulum; sarcoplasmic reticulum membrane
Genetic constraint (gnomAD): Loss-of-function variants: 40 observed, 59.95 expected, observed/expected ratio (o/e) 0.67, 90% interval 0.52 to 0.87. The upper end of that interval is the gene's LOEUF score, 0.87, which puts it in group 3 of 6, group 1 being the genes least tolerant of losing a copy. Missense variants: 788 observed, 863.71 expected, observed/expected ratio (o/e) 0.91, 90% interval 0.86 to 0.97. Synonymous variants: 288 observed, 312.84 expected, observed/expected ratio (o/e) 0.92, 90% interval 0.83 to 1.01.
Homologues: Orthologues: chimpanzee HRC (95% identical), macaque HRC (82% identical), dog HRC (68% identical), pig HRC (63% identical), guinea pig HRC (56% identical), mouse Hrc (53% identical), rat Hrc (51% identical), zebrafish hrc (17% identical).
Diseases named in the same sentence as HRC in open-access papers:
HRC is named in the same sentence as 14 diseases in open-access papers, as found by Europe PMC text mining. Sharing a sentence is not in itself a finding about the gene and the disease. The quoted sentences say what the papers report.
hepatocellular carcinoma (3 papers, 2015 to 2021). A malignant tumor that arises from hepatocytes. "Histidine-rich calcium binding protein (HRC) is markedly overexpressed in hepatocellular carcinoma (HCC) and is significantly correlated with metastasis." (PMID 34400882, 2021). "The histidine-rich calcium-binding protein (HRC) is a regulator of Ca2+ homeostasis and it plays a significant role in hepatocellular carcinoma (HCC) progression." (PMID 27881436, 2017). "In our study, for the first time, we found that HRC was significantly upregulated in hepatocellular carcinoma (HCC) tissues compared with the pericarcinoma tissues, and the expression of HRC was positively correlated with the metastatic potentials of HCC cells." (PMID 25762622, 2015).
cardiomyopathies (2 papers, 2017 to 2023). "Therefore, dysfunction of factors that regulate Ca2+ homeostasis, such as the histidine-rich calcium-binding protein (HRC), may contribute to the development and progression of inherited cardiomyopathies." (PMID 37958923, 2023).
dilated cardiomyopathy (2 papers, 2017 to 2018). Cardiomyopathy which is characterized by dilation and contractile dysfunction of the left and right ventricles. "Mutations in ABCC9 gene can cause dilated cardiomyopathy and a genetic variant in the HRC gene has been linked to ventricular arrhythmia and sudden death in dilated cardiomyopathy." (PMID 29257745, 2017).
failure heart (2 papers, 2012 to 2021). "Taken together, these results suggest that HRC-KD induces cardiac apoptosis through activation of CaMKII/p38 MAPK signaling pathways, causing deterioration of heart function under the heart failure conditions." (PMID 22952658, 2012). "Histidine-rich calcium binding protein (HRC) can affect Ca2+ cycling in the sarcoplasmic reticulum (SR) that could cause the mitochondrial death pathway and enhance cardiac function in failure heart." (PMID 34408773, 2021).
gastric cancer (2 papers, 2022 to 2024). A primary or metastatic malignant neoplasm involving the stomach. "Here, we demonstrated that HRC expression was upregulated in human gastric cancer (GC) samples, and its expression level was closely correlated with the overall survival (OS) rate of GC patients and the malignant potential of GC cell lines." (PMID 35281855, 2022). "Notably, the histidine-rich calcium-binding protein (HRC), a calcium-binding protein, has been observed to modulate the Raf/MEK/ERK pathway through calcium (Ca) and calmodulin (CaM) signaling, thereby impacting the epithelial-mesenchymal transition (EMT) in gastric cancer (GC) cells." (PMID 38370477, 2024).
Cirrhosis (1 paper, 2017). A chronic disorder of the liver in which liver tissue becomes scarred and is partially replaced by regenerative nodules and fibrotic tissue resulting in loss of liver function. "The results showed that the expression of HRC was gradually increased along with the severity of liver fibrosis, and HRC was significantly overexpressed in cirrhosis." (PMID 27881436, 2017).
liver cancer (1 paper, 2015). An epithelial or non-epithelial malignant neoplasm that arises from the liver. "In addition, we also analysed the expression of HRC in a panel of human liver cancer cell lines." (PMID 25762622, 2015).
liver fibrosis (1 paper, 2017). "In addition, we detected the expression of HRC in a thioacetamide (TAA)-induced liver fibrosis animal model, which is widely used for the study of liver fibrosis." (PMID 27881436, 2017). "In conclusion, our study demonstrated that knockdown of HRC inhibit HSC activation and liver fibrosis in vitro, and further studies should be carried out to clarify the role of HRC in liver fibrosis in vivo." (PMID 27881436, 2017). "Knockdown of HRC reduced the expression of α-SMA, along with other genes relative to liver fibrosis, such as Col1A1, Col3A1 and CTGF." (PMID 27881436, 2017).
tumor (4 papers, 2015 to 2023). "Subsequently, we verified the relationship between the expression of HRC in the tumor tissues of patients with GC using a GC tissue microarray and revealed that high expression of HRC was a potential predictor of poor prognosis." (PMID 35281855, 2022). "The positive expression of HRC was observably correlated with tumor size, tumor encapsulation, and tumor-node-metastasis (TNM) stage." (PMID 34400882, 2021). "This pathway can be activated in GC by overexpression of HRC (Histidine-rich calcium binding protein), upregulation of MAGOH and MAGOHB, and overexpression of YAP1 (Yes-associated protein 1), and subsequently promotes the tumour cell proliferation, migration, and invasion." (PMID 37037864, 2023). "Our results showed that the expression of HRC was correlated with tumor size and T stage." (PMID 35281855, 2022). "In addition, HRC expression was significantly correlated with tumor size, tumor encapsulation and higher tumor-nodule-metastasis (TNM) stage." (PMID 34400882, 2021). "We wondered whether HRC might be involved in tumor metastasis." (PMID 25762622, 2015). "The expression level of HRC was upregulated in 371 HCC tissues compared with that in 50 normal liver tissue samples according to the TCGA database, and the data showed that HRC was significantly correlated with the degree of malignancy of HCC including tumor stage and lymph node metastasis." (PMID 34400882, 2021).
HRC also shares sentences with these, for which no sentence is quoted: Arrhythmia (1 paper); osteosarcoma (1); Paroxysmal atrial fibrillation (1); sudden cardiac death (1); Ventricular arrhythmia (1).